RN7SKP99 (RN7SK pseudogene 99)
Gene: Miscellaneous RNA gene on chromosome 14 (57,837,354 to 57,837,660, reverse strand). Ensembl gene ENSG00000252837.
Homologues: Orthologues: chimpanzee 7SK (85% identical). Paralogues in human: RN7SKP184 (58% identical), RN7SKP33 (58% identical), RN7SKP44 (58% identical), RN7SKP58 (57% identical), RN7SKP180 (57% identical), 7SK (57% identical), RN7SKP294 (57% identical), RN7SKP137 (56% identical), RN7SKP146 (56% identical), RN7SKP30 (56% identical), RN7SKP79 (56% identical), RN7SKP163 (56% identical), and 283 more.